MAGEA11 (MAGE family member A11)
Description:
Acts as androgen receptor coregulator that increases androgen receptor activity by modulating the receptors interdomain interaction. May play a role in embryonal development and tumor transformation or aspects of tumor progression.
Synonyms: CT1.11; MAGE11; MAGE-11; MAGEA-11; MGC10511
Tractability: PROTAC: ubiquitination databases record sites on it.
Gene: Protein-coding gene on chromosome X (149,688,228 to 149,717,268, forward strand). Ensembl gene ENSG00000185247.
Subcellular location: Nucleus; Cytoplasm
Subcellular location (Human Protein Atlas): Nuclear bodies; Nucleoplasm; Cytosol
Gene Ontology:
Molecular function: protein binding; histone deacetylase binding
Biological process: negative regulation of transcription by RNA polymerase II
Cellular component: cytosol; nuclear body; nucleoplasm; nucleus; cytoplasm
Homologues: Orthologues: chimpanzee MAGEA11 (99% identical), chimpanzee MAGEA11 (92% identical), mouse Magea13 (30% identical), rat Magea13 (29% identical), zebrafish ndnl2 (16% identical), Drosophila melanogaster MAGE (13% identical). Paralogues in human: MAGEA4 (46% identical), MAGEA8 (45% identical), MAGEA1 (44% identical), MAGEA3 (44% identical), MAGEA6 (44% identical), MAGEA12 (44% identical), MAGEA9 (44% identical), MAGEA9B (44% identical), MAGEA2 (43% identical), MAGEA2B (43% identical), MAGEA10 (42% identical), MAGEB16 (36% identical), and 25 more.
Diseases named in the same sentence as MAGEA11 in open-access papers:
MAGEA11 is named in the same sentence as 35 diseases in open-access papers, as found by Europe PMC text mining. Sharing a sentence is not in itself a finding about the gene and the disease. The quoted sentences say what the papers report.
prostate carcinoma (12 papers, 2017 to 2023). A carcinoma that arises from epithelial cells of the prostate gland. "For example, MAGEA3 and MAGEA6 are both associated with colorectal and lung cancers, and MAGEA6 and MAGEA11 are coexpressed in prostate cancer." (PMID 34202157, 2021). "DNA hypomethylation-mediated MAGEA11 activation was also shown to be involved in oncogenesis in prostate cancer." (PMID 36980267, 2023). "Studies have found that prostate cancer has abnormally high levels of MAGEA11 and high androgen receptor protein expression, and increased MAGEA11 expression is directly related to the progression of prostate cancer." (PMID 36292195, 2022). "In particular, MAGEA3 and MAGEA6 expression are highly correlated in colon and lung cancer, as is MAGEA6 and MAGEA11 expression in prostate cancer." (PMID 34202157, 2021). "In prostate cancer, MAGEA11 is an androgen responsive gene and, following exposure of cells to androgens, co-localises to the nucleus with AR, where it functions as an AR co-regulator increasing AR transcriptional activity." (PMID 31256208, 2019). "Part of their findings demonstrate that MageA11 is a co-regulator of the Androgen Receptor (AR) and overexpressed in human prostate cancer samples." (PMID 28542476, 2017). "Database search confirmed that MageA11 and MageA6 are co-expressed in human prostate cancer samples." (PMID 28542476, 2017). "MAGEA11 increases AR transcriptional activity during prostate cancer progression." (PMID 32626651, 2020).
breast carcinoma (8 papers, 2007 to 2024). "MAGEA11 was previously found to be highly expressed in breast cancer, bladder cancer, and laryngeal squamous cell carcinoma; the positive expression of this gene was associated with the progression of malignant tumors, thus leading to poor survival." (PMID 38561388, 2024). "Of 16 CTAGs examined in the first panel of 42 breast cancer samples, seven antigens were found not to be expressed in any of the specimens: SSX2, SSX4, CTAG2, CAGE1, MAGEA1, MAGEA4 and MAGEA11." (PMID 17650306, 2007).
esophageal squamous cell carcinoma (6 papers, 2018 to 2025). Esophageal squamous cell carcinoma (ESCC) is a type of esophageal carcinoma (EC) that can affect any part of the esophagus, but is usually located in the upper or middle third. "The high expression of metastasis related MAGEA11 is a worse prognosis in esophageal squamous cell carcinoma." (PMID 36807122, 2023). "105B potently degrades BET proteins in U2OS osteosarcoma cell lines (BRD4 DC50 = 0.130 nM, Dmax = 78%) and KYSE180 esophageal squamous cell carcinoma cell lines (DC50 = 40 nM, Dmax = 70%), but shows no degradation in non-cancerous, MAGEA11-deficient HEK293T cells." (PMID 41279184, 2025).
melanoma (6 papers, 2016 to 2023). A malignant, usually aggressive tumor composed of atypical, neoplastic melanocytes. "Melanoma-associated antigen 11 (MAGEA11), originally identified in melanomas as a cancer germline antigen, has been shown to function as an AR co-activator." (PMID 30791431, 2019). "Indeed, we found that the majority of epitopes derived from MAGEA11 were only expressed in melanoma samples." (PMID 36099422, 2023). "When querying epitopes derived from MAGEA11 in melanoma, we obtained six entries." (PMID 36099422, 2023).
gastric cancer (5 papers, 2021 to 2024). A primary or metastatic malignant neoplasm involving the stomach. "Receiver Operating Characteristic (ROC) curve analysis was carried out to examine the diagnostic utility of MAGEA11 in differentiating gastric cancer samples from normal tissues." (PMID 36292195, 2022). "Recently, scientific interest in MAGEA11 has increased, but its association with gastric cancer is limited." (PMID 36292195, 2022). "Our study showed that upregulation of MAGEA11 in gastric cancer was significantly associated with decreased survival and invasion by immune infiltration." (PMID 36292195, 2022). "We believe that MAGEA11 is associated with the poor prognosis of gastric cancer because patients with high expression of MAGEA11 had relatively shorter survival times." (PMID 36292195, 2022). "Our study found that upregulated MAGEA11 in gastric cancer was significantly associated with lower survival and invasion by immune infiltration." (PMID 36292195, 2022). "To examine the expression of MAGEA11 mRNA in gastric cancer, we analyzed the MAGEA11 expression data in TCGA." (PMID 36292195, 2022). "Subsequently, MAGEA11 mRNA expression and overall survival (OS) were investigated in gastric cancer patients using the Kaplan–Meier (KM) curve." (PMID 36292195, 2022). "These outcomes showed that the mRNA expression of MAGEA11 was upregulated in gastric cancer tissues." (PMID 36292195, 2022). "The results showed that the expression of MAGEA11 mRNA in gastric cancer tissues was significantly higher than that in normal tissues." (PMID 36292195, 2022). "Preliminary studies support that PF-04217903, 4SC-202, Indibulin, Tipifarnib, ETHINYL ESTRADIOL, and Okadaic acid can target MAGEA11, which is expected to make new progress in gastric cancer treatment." (PMID 36292195, 2022). "The expression of MAGEA11 in pan-cancer and the receiver operating characteristic (ROC) and survival impact of gastric cancer were evaluated by The Cancer Genome Atlas (TCGA)." (PMID 36292195, 2022). "In this paper, we found that MAGEA11 was significantly highly expressed in gastric cancer patients, and it was correlated with the survival of patients." (PMID 36292195, 2022). "In the present study, we found for the first time that MAGEA11 is upregulated and has poor prognosis in gastric cancer and may play a specific role in immune infiltration." (PMID 36292195, 2022). "It is suggested that MAGEA11 may be a potential biomarker and immunotherapy target for gastric cancer." (PMID 36292195, 2022). "In this research, we investigated the expression of MAGEA11 in gastric cancer and used bioinformatics analysis to evaluate its correlation with the prognosis and immune infiltration of gastric cancer patients and the sensitivity to different chemotherapeutic drugs." (PMID 36292195, 2022). "Finally, we discovered for the first time in this study that MAGEA11 is highly upregulated in gastric cancer as a potential prognostic marker and may play a specific role in immune infiltration." (PMID 36292195, 2022). "However, in gastric cancer, the prognostic significance of MAGEA11 and its relationship with immune infiltration remain largely unknown." (PMID 36292195, 2022). "In contrast to gastric mucosa epithelial cell line GES-1, transcriptional levels of PAPPA2, MPO, MAGEA11, DEPP1, CPZ, and COLEC12 were higher in gastric cancer cell lines HGC-27, MKN-28 and AGS, with lower transcriptional level of CYTL1." (PMID 37124627, 2023). "Higher levels of PAPPA2, MPO, MAGEA11, DEPP1, CPZ, and COLEC12 and lower level of CYTL1 were proven in gastric cancer cells versus controls." (PMID 37124627, 2023). "This study experimentally verified the levels of DNA repair-relevant genes, with higher levels of PAPPA2, MPO, MAGEA11, DEPP1, CPZ, and COLEC12 and lower level of CYTL1 in gastric cancer cells versus controls." (PMID 37124627, 2023).
gastric cancer (continued). "The MAGEA11 mRNA expression level in gastric cancer tissues (n = 375) was significantly higher than that in normal tissues (n = 32), according to unpaired data analysis." (PMID 36292195, 2022). "At present, there is no clear research report on the role of MAGEA11 in human gastric cancer, and it is worthy of attention to explore the expression of MAGEA11 and its effect on gastric cancer." (PMID 36292195, 2022). "At the same time, we supplemented the GTEx database and the GEO database (GSE54129) for joint analysis and also found that the expression of MAGEA11 in gastric cancer was significantly higher than that in normal tissues." (PMID 36292195, 2022).
bladder cancer (3 papers, 2022 to 2024). "A data analysis of bladder cancer patients further uncovers the possibilities of utilizing MAGEA2, MAGEA3, MAGEA4, MAGEA6, MAGEA10, MAGEA11, and MAGEA12 members as diagnostic biomarkers for bladder cancer." (PMID 38254738, 2024). "It was found that frequencies of genomic alterations among MAGEA family members in bladder cancer were MAGEA1 1.8%, MAGEA2 1.6%, MAGEA3 1.9%, MAGEA4 1.6%, MAGEA6 2.6%, MAGEA8 1.7%, MAGEA10 2%, MAGEA11, 2.1%, and MAGEA12 2.4%." (PMID 38254738, 2024). "Interestingly, MAGEA2, MAGEA3, MAGEA4, MAGEA6, MAGEA10, MAGEA11, and MAGEA12 exhibited significant differences in their expression in bladder cancer compared to normal bladder samples." (PMID 38254738, 2024).
glioma (2 papers, 2013 to 2025). A benign or malignant brain and spinal cord tumor that arises from glial cells (astrocytes, oligodendrocytes, ependymal cells). "MAGEA11 and MAGEC1 were hypermethylated in AR-negative gliomas (Kruskal–Wallis < 0.05) as well as in IDH-mutant low-grade tumors." (PMID 41153666, 2025).
osteosarcoma (2 papers, 2023 to 2025). A usually aggressive malignant bone-forming mesenchymal neoplasm, predominantly affecting adolescents and young adults. "The PROTACs were initially screened in U2OS osteosarcoma cells due to their known sensitivity to BRD4 inhibition, degradation, and MAGEA11 expression, confirmed via western blot.25, 28, 29 The PROTACs were screened in a 24 hour, 4-point titration from 10 - 0.01 μM concentrations." (PMID 41279184, 2025).
colon cancer (1 paper, 2021). "For example, in prostate, ovarian, and colon cancer cells, the MAGEA1 and MAGEA11 promoters are hypomethylated, and their expression is increased." (PMID 34202157, 2021).
Gynecomastia (1 paper, 2020). Abnormal development of large mammary glands in males resulting in breast enlargement. "MAGEA family members, in particular MAGEA2, MAGEA11, and MAGEC2, showed the hypomethylation of several CpGs (p < 0.01) in MBC compared to gynecomastia." (PMID 32626651, 2020).
hypoglycaemia (1 paper, 2014). "Our array data indicated that two MAGE genes were demethylated by hypoxia (MAGEA11) and hypoglycaemia (MAGEB1), though no induction in expression was observed." (PMID 25079072, 2014).
infertile (1 paper, 2019). "Enhanced MAGEA11 and AR-mediated transcriptional regulation may impact on a correct endometrial decidualisation response, subsequently affecting endometrial receptivity in these infertile women." (PMID 31256208, 2019).
ovarian carcinoma (1 paper, 2019). A malignant neoplasm originating from the surface ovarian epithelium. "MAGEA11 gene expression was significantly elevated in ovarian carcinomas, compared with normal ovary tissues." (PMID 30791431, 2019). "Moreover, in ovarian cancer, the expression of MAGEA11 was found to correlate positively with that of other cancer germline antigen genes and inversely with DNA methylation on its promoter activity." (PMID 30791431, 2019).
cancer (15 papers, 2016 to 2025). A tumor composed of atypical neoplastic, often pleomorphic cells that invade other tissues. "Methylation of melanoma associated antigen 11 (MAGEA11) which was a co-activator of AR was related to poor prognosis of cancer." (PMID 35886904, 2022). "Moreover, based on the RNA expression of MAGEA11 across SKCM and normal tissues, we found that the expression level of MAGEA11 in the testis far exceeds that of other tissues, and high expression of MAGEA11 was associated with worse survival of cancer patients." (PMID 36099422, 2023). "Here, we report a tissue-specific PROTAC that recruits the cancer-(and placental/sperm-) specific E3 ligase scaffolding protein MAGEA11." (PMID 41279184, 2025). "MAGEA11, a cancer germline antigen, is correlated with tumor progression, drug resistance, and poor prognosis in human cancers." (PMID 35898512, 2022). "MAGEA6 and MAGEA11 through UALCAN database based on cancer genome atlas (TCGA) were reported." (PMID 35022469, 2022). "According to this information, MAGEA11 mRNA expression was abnormal in various cancer types." (PMID 36292195, 2022). "This work reports the first example of a PROTAC recruiting a tissue-specific E3 ligase for cancer-restricted degradation of BET proteins and highlights the need for further development of MAGEA11-recruiting degraders." (PMID 41279184, 2025). "Together these results show that 105B is highly potent in two cancer cell lines expressing MAGEA11 and demonstrates no BRD4 degradation in HEK293T cells." (PMID 41279184, 2025).
tumor (15 papers, 2009 to 2025). "In correlation analysis, MAGEA11 mRNA expression was found to be associated with tumor purity and immune invasion." (PMID 36292195, 2022). "We observed the genetically altered status of MAGEA11 in different tumor samples from the TCGA cohort." (PMID 36292195, 2022). "The relationship between MAGEA11 and immune infiltration was determined by the Tumor Immunity Estimation Resource (TIMER) and the Tumor Immune System Interaction Database (TISIDB)." (PMID 36292195, 2022). "Among the atlas of epitopes in IEAtals, several tumor-specific epitopes indeed have been validated in previous studies, such as RP11-726G1.1 and MAGEA11." (PMID 36099422, 2023). "On the other hand, MAGEA11 recruits HUWE1 E3 ubiquitin ligase for modulating core oncogenic and tumour suppressor pathways." (PMID 38136576, 2023). "Tumor-specific demethylation was found in GRIN1 (p = 0.005), MAGEA11 (p = 0.001), and MAGEA2 (p = 0.002)." (PMID 19305507, 2009). "The epigenetic reactivation of TKTL1, H19, MAGEA2, MAGEA3/6, MAGEA4, MAGEA11, GPR17, GRIN1, and C19ORF28, genes located at diverse chromosomal loci, occurs simultaneously in individual primary tumors from multiple tumor types." (PMID 19305507, 2009).
adenocarcinoma (1 paper, 2022). A common cancer characterized by the presence of malignant glandular cells. "The findings implied that MAGEA11 may be a promising biomarker to distinguish normal tissue from adenocarcinoma tissue." (PMID 36292195, 2022).
MAGEA11 also shares sentences with these, for which no sentence is quoted: esophageal cancer (3 papers); head and neck squamous cell carcinoma (3); lung carcinoma (3); renal cell carcinoma (3); bladder tumor (1); colorectal cancer (1); esophageal adenocarcinoma (1); esophageal tumor (1); head and neck carcinoma (1); infection (1); laryngeal squamous cell carcinoma (1); non-small cell lung carcinoma (1); pheochromocytoma (1); polycystic ovary syndrome (1); prostate (1); prostate tumors (1); retinoblastoma (1); stomach cancer (1); thymoma (1).